CASP8 (caspase 8)
Diseases named in the same sentence as CASP8 in open-access papers (continued):
Sharing a sentence is not in itself a finding about the gene and the disease.
non-small cell lung carcinoma (19 papers, 2011 to 2025). A group of at least three distinct histological types of lung cancer, including non-small cell squamous cell carcinoma, adenocarcinoma, and large cell carcinoma. "The aim of our study was to determine the impact of polymorphisms in the CASP-8 gene encoding caspase 8 on the prognosis in non-small-cell lung cancer (NSCLC)." (PMID 33800294, 2021). "Additionally, GMEB1 inhibited the activation of pro-caspase 8 and apoptosis in non-small cell lung cancer (NSCLC) cell via CFLARL stabilization." (PMID 31046799, 2019). "Although it remains to be determined how gemcitabine induces caspase-8 activation, it has also been reported that gemcitabine induces apoptosis in non-small cell lung cancer (NSCLC) cells by increasing expression of functionally active Fas (CD95, APO-1) and up-regulating Fas ligand (FasL)." (PMID 26894857, 2016). "Interestingly, our recent study found that although caspase-8 could be directly activated by caspase-3, the intrinsic pathway was not enhanced by caspase-3 during artemisinin-induced apoptosis in non-small cell lung cancer cells (A549 cells)." (PMID 28182780, 2017). "In non-small cell lung cancer (NSCLC), USP40 suppresses polyubiquitination of anti-apoptotic protein CFLARL, and GMEB1 promotes CFLARL stability via USP40, followed by inhibition of CASP8 precursor activation and apoptosis." (PMID 38308285, 2024). "The AS PTO downregulated c-FLIP and resulted in caspase-8 activation and apoptosis induction in non-small cell lung cancer (NSCLC) cells, but not in normal lung cells." (PMID 22348197, 2011). "Human SCLC, but not non-small cell lung cancer (NSCLC) cell lines, lacked caspase 8 expression and, as a result of this, were resistant to induction of extrinsic apoptosis." (PMID 41413044, 2025).
lymphoma (18 papers, 2010 to 2025). A malignant (clonal) proliferation of B- lymphocytes or T- lymphocytes which involves the lymph nodes, bone marrow and/or extranodal sites. "These investigators used a genetically tractable in vivo myc driven lymphoma model in which death receptor signaling was compromised due to overexpression of CrmA, a viral caspase-8 inhibitor, or due to deficiency of TRAIL." (PMID 20145726, 2010). "Approximately 50% of B cell-specific Casp8−/− mice developed lymphomas with elevated chromosomal instability within 60 weeks." (PMID 38637559, 2024). "There were a number of genes related to apoptosis including Bcl2 (B-cell CLL/lymphoma), Cflar (CASP8 and FADD-like apoptosis regulator), and Nkg7 (natural killer cell group 7 sequence)." (PMID 36552094, 2022). "Significant increases in activated caspase 3, caspase 8, and caspase 9 activities were observed in lymphoma cells as compared to controls after 48 h of treatment with hypoxic and normoxic hWJSC-CM." (PMID 32377203, 2020). "The percentages of lymphoma cells that were positive for activated caspase 8 activities were hWJSC-CM (21% O2): 32.9 ± 1.15%, hWJSC-CM (10% O2): 31.8 ± 0.64%, hWJSC-CM (5% O2): 46.2 ± 1.19%, and control: 14.8 ± 0.56%." (PMID 32377203, 2020). "The role of EGCG and a radiolytic product in triggering the Fas-caspase-8-medicated pathway in lymphoma U937 cells has been demonstrated by others." (PMID 25647297, 2015). "A single study has examined the molecular mechanism of apoptosis induction by PCI-24781 and reported that both caspase-8 and -9 are cleaved and activated by the HDACi in lymphoma lines." (PMID 20145726, 2010). "Likewise, we also demonstrated an increase in the activities of the apoptosis initiators Caspase-8 and -9 and the executioner Caspase-3 in lymphoma cells treated with the phytocannabinoids THC and CBD or with the synthetic cannabinoid WIN." (PMID 38672512, 2024). "Cluster 1 (top right) included genes such as CD79A, PTPRC, EZH2, MMP9, IKBKB, or CASP8, which were upregulated in GCB lymphomas (top right colored in orange)." (PMID 41472741, 2025). "24S-HC can also induce apoptosis in human T-lymphoma Jurkat cells via activation of caspase 8, a mechanism not observed in SH-SY5Y cells." (PMID 28346482, 2017). "Oxidation of pro-caspase-8 in cells would generate an intramolecular disulfide that could not be detected with this methodology; therefore, Jurkat T lymphoma cells were incubated with TS for 2 h to induce caspase-8 cleavage (immunoblot lanes 2 and 5)." (PMID 37150321, 2023). "Other genes, such as IKBKB, PTPRC, CASP8, or CD79B, with small p-values did not have a great magnitude of changes between the lymphoma subtypes." (PMID 41472741, 2025). "Its endogenous expression has been well characterized in lymphoid cancer cell lines where Caspase-10 can be recruited to the DISC complex, similarly to Caspase-8, although it neither affects Caspase-8 activation nor it can compensate for Caspase-8 deficiency." (PMID 30501030, 2018).
osteosarcoma (18 papers, 2009 to 2025). A usually aggressive malignant bone-forming mesenchymal neoplasm, predominantly affecting adolescents and young adults. "The preliminary exploration on the molecular mechanism of MEX3A in osteosarcoma cells showed that the induction of apoptosis needs the participation of a series of apoptosis- associated factors, such as upregulation of Caspase 3, Caspase 8 and HSP60, downregulation of HSP27 and XIAP." (PMID 33827584, 2021). "We found that genetic inhibition of VPS4 triggered both caspase-8 (CASP8)-dependent apoptosis and caspase-independent cell death in osteosarcoma cells." (PMID 40147096, 2025). "A study proved that treating osteosarcoma MG-63 cells with corosolic acid led to the activation of caspase-8, -9, and -3, suggesting the stimulation of both the intrinsic and extrinsic pathways in these cancer cells." (PMID 37009004, 2023). "Consistently, we found that MEX3A knockdown induced apoptosis of osteosarcoma cells, resulting in the activation of Caspase-3, Caspase-8 and HSP60." (PMID 33827584, 2021). "In this study, we demonstrated that Licochalcone A suppressed cell viability through the induction of cell cycle arrest at G2/M phase and caspase 8/3-dependent apoptosis in osteosarcoma cell lines." (PMID 31269698, 2019). "For example, CDDO and its derivates CDDO-Me and CDDO-Im have been reported to activate the extrinsic apoptotic pathway directly via caspase-8 and caspase-3 in osteosarcoma cells by a mechanism that acts independently of cytochrome-c." (PMID 26751572, 2016). "One study proposes that depsipeptide, (also called FR901228) can upregulate FasL at the mRNA level in osteosarcoma cells resulting in caspase-8 and -3 activation." (PMID 20145726, 2010). "The time-dependent activation of Caspase-8 by treatment with avicin D was also confirmed in a human osteosarcoma cell line, U2OS." (PMID 20046832, 2009). "We therefore speculate that, in these osteosarcoma cells, TNFα/SM-164-induced necroptosis triggered by caspase inhibition resulted from suppression of caspase-8-mediated cleavage of an as-yet unidentified substrate." (PMID 27129149, 2016). "In this report, we showed that Licochalcone A treatment induced cleaved-caspase 8 and caspase 3, but decreased the levels of Bax and cleaved-caspase 9, indicating that Licochalcone A triggers apoptosis that mediated by the extrinsic pathways in osteosarcoma cell lines." (PMID 31269698, 2019). "More specifically, in osteosarcoma, a study mentioned that IFN-γ sensitizes osteosarcoma cells to CD95R, inducing apoptosis through the upregulation of CD95R and caspase-8." (PMID 38748263, 2024). "Though the exact function of expression of CTLA-4 on tumor cells is unknown, incubating the cells with CTLA-4 ligands CD80 or CD86 induced apoptosis in human osteosarcoma cell line HOS cells through caspase-3 and caspase-8 activation." (PMID 33823818, 2021). "The effect of ClC-5 downregulation on osteosarcoma cell apoptosis and viability was abolished by caspase-3 and caspase-9 inhibitors, but not caspase-8 inhibitor." (PMID 33614474, 2020). "In osteosarcoma cells, differentiation induced by CDDO is abrogated by the overexpression of the extrinsic caspase-8 inhibitor cytokine response modifier A (CrmA), suggesting that CDDO-induced differentiation is mediated by caspase-8 activity." (PMID 31766211, 2019). "In this study, by differential gene expression we found several genes that might be the AR downstream target genes in osteosarcoma, such as cyclin G2, CDC20, Caspase-8, JNK." (PMID 28262798, 2017). "We infer that, in osteosarcoma cells, IAP antagonist-mediated degradation of cIAP1 enables formation of the ripoptosome and activation of caspase-8, which can stimulate caspase-3/7 activity if the IAP antagonist permits this by relieving XIAP-mediated inhibition." (PMID 27129149, 2016).
small cell lung carcinoma (18 papers, 2009 to 2025). Small cell lung cancer (SCLC) is a highly aggressive malignant neoplasm, accounting for 10-15% of lung cancer cases, characterized byrapid growth, and early metastasis. "Moreover, DED expression in other caspase-8-deficient tumors (small cell lung carcinoma), similarly impacted proliferation and resulted in multinucleation, thereby validating the concept that DEDs contribute to mitotic crisis and cell cycle arrest." (PMID 19924290, 2009). "For Kyoto Encyclopedia of Genes and Genomes (KEGG) pathways, GSEA further highlighted that high CASP8 expression in patients was linked to increased activity in axon guidance, extracellular matrix (ECM) receptor interactions, and pathways relevant to small cell lung cancer." (PMID 38186679, 2023). "Loss of caspase-8 expression was also found in small cell lung carcinoma (SCLC), but interestingly, was completely absent in non-SCLCs." (PMID 27843441, 2016). "In small cell lung cancer cells lacking caspase 8, TRAIL induced proliferation, which could be inhibited using ERK1/2 siRNA." (PMID 34527710, 2021).
dermatitis (17 papers, 2014 to 2025). An inflammatory process affecting the skin. "Our genetic studies showed that epidermis-specific ablation of FADD or caspase-8 caused skin inflammation by inducing RIPK3-MLKL-dependent necroptosis of keratinocytes." (PMID 38849574, 2024). "The same happens on the skin where keratinocyte-specific deletion of Hoip and Hoil-1 results in severe dermatitis caused by TNFR1-induced caspase-8-mediated apoptosis." (PMID 34434197, 2021). "In summary, we provide strong evidence that Sharpin deficiency sensitizes keratinocytes to TNF/TNFR1-induced, caspase-8-mediated apoptosis, and that this defect appears to drive the cpdm dermatitis." (PMID 25443632, 2014). "One of these mice developed the skin phenotype at 10 months of age, indicating that the single allele of Casp8 is enough to eventually cause dermatitis." (PMID 25443632, 2014). "Strikingly, combined Ripk3 deficiency and Casp8 heterozygosity completely prevented the cpdm dermatitis in all but one of the mice analyzed at 42 to 45 weeks of age, prevented liver inflammation and grossly restored splenic architecture." (PMID 25443632, 2014). "Next, we sought to address whether FADD/caspase-8-dependent apoptosis of Sharpin-deficient keratinocytes induces TNF-dependent skin inflammation in Sharpincpdm/cpdm mice." (PMID 25443631, 2014). "Accordingly, mice bearing deletion of Casp8 from epidermal keratinocytes (Casp8E-KO) presented with severe skin inflammation leading to lethality by P7." (PMID 38783091, 2024). "At E17.5, both Casp8−/−Tnfr1−/−Trif−/− and Casp8−/−Tnfr1−/−Zbp1−/− embryos had dermatitis that primarily affected the dorsal skin." (PMID 38548850, 2024). "Specifically, TNF-induced apoptosis is responsible for skin inflammation since Casp8 heterozygosity can significantly ameliorate the dermatitis, while multi-organ inflammation is predominantly driven by RIPK3/MLKL-induced necroptosis." (PMID 38783091, 2024). "Here we show that ZBP1 causes skin inflammation by inducing RIPK3-mediated necroptosis and RIPK1-caspase-8-mediated apoptosis in keratinocytes." (PMID 38849574, 2024). "Here we identified a critical interplay between RIPK3-MLKL-dependent necroptosis and FADD-caspase-8-mediated apoptosis that controls skin inflammation downstream of TNFR1 and ZBP1." (PMID 38849574, 2024). "Collectively, these results showed that ZBP1ca expression caused skin inflammation by inducing RIPK3-MLKL-dependent necroptosis and to a lesser extent caspase-8-dependent apoptosis in keratinocytes." (PMID 38849574, 2024). "Caspase-8 heterozygosity significantly delays dermatitis onset, while co-deletion of FADD (in the skin) and RIPK3 was required to entirely ablate skin inflammation, implying that inflammation is primarily driven by apoptosis, with a minor role for necroptosis." (PMID 33924766, 2021). "We provide genetic and pharmacological evidence that the postnatal lethal dermatitis in HoipE-KO and Hoil-1E-KO mice is caused by TNFR1-induced, caspase-8-mediated apoptosis that occurs independently of the kinase activity of RIPK1." (PMID 30254289, 2018). "TNFR1-induced apoptosis can proceed through caspase-8 and BID, but reduction in or loss of these players generally did not suppress inflammation, although Casp8 heterozygosity significantly delayed dermatitis." (PMID 25443632, 2014). "The dermatitis in mice with keratinocyte-specific deletion of caspase 8 (Casp8tm1Wll) is characterized by accumulation of eosinophils and macrophages and increased expression of type 2 cytokines similar to Sharpincpdm mice." (PMID 24465642, 2014). "Given the prominent role that caspase-8 plays in the dermatitis, it would be expected that if the intrinsic apoptosis pathway is engaged it should be downstream of caspase-8 and require cleavage of the BH3 protein, BID." (PMID 25443632, 2014). "Nonetheless, the combination of the inhibition of RIPK3-MLKL-dependent necroptosis and RIPK1-caspase-8-driven cell death could fully prevent skin inflammation mediated by ZBP1ca." (PMID 40006996, 2025).
dermatitis (continued). "Caspase-8 ablation combined with mutation of the MLKL phosphorylation sites completely prevented skin lesion development in ZBP1caE-het mice, demonstrating that ZBP1ca induces skin inflammation by triggering necroptosis and caspase-8-mediated apoptosis." (PMID 38849574, 2024). "Importantly, ZBP1ca induced caspase-8-mediated skin inflammation by RHIM-dependent but kinase activity-independent RIPK1 signaling." (PMID 38849574, 2024). "Indeed, while concomitant deletion of RIPK3 and Caspase-8 completely prevents the inflammatory lesions, loss of TNFR1 delays the onset of dermatitis, but mutant mice still succumb later in life due to severe skin inflammation." (PMID 35740456, 2022). "Keratinocyte-specific deletion of caspase 8 and the FAS-associated death domain (FADD) adaptor protein result in increased necroptosis of keratinocytes and cutaneous inflammation that is strikingly similar to the dermatitis in SHARPIN-deficient mice." (PMID 24465642, 2014). "Tumour necrosis factor (TNF) and caspase-8-driven cell death causes the pathogenesis of Sharpincpdm mice; however, the role of mind bomb 2 (MIB2), a pro-survival E3 ubiquitin ligase involved in TNF signaling, in skin inflammation remains unknown." (PMID 38156288, 2024). "Moreover, transgenic expression of C-terminally truncated constitutively active ZBP1 (ZBP1ca) in mouse epidermis caused skin inflammation that was only partially inhibited by abrogation of RIPK3-MLKL-dependent necroptosis and fully prevented by combined deficiency in MLKL and caspase-8." (PMID 38849574, 2024). "However, the dermatitis in CASP8-deficient mice is not affected by absence of TNF or IL1-receptor signaling, in contrast to Sharpincpdm mice." (PMID 24465642, 2014). "Moreover, the skin inflammation in these mice was driven by TNF, epithelial TNFR1 and RIPK1 kinases, FADD/ caspase-8-mediated cell death, and innate immune sensors, adaptors and components of inflammasomes." (PMID 40006996, 2025). "Here we show that combined ablation of TNFR1 and ZBP1 fully prevented skin inflammation in FADDE-KO mice, demonstrating that ZBP1-mediated necroptosis drives TNFR1-independent skin inflammation upon keratinocyte-specific inhibition of FADD/caspase-8 signaling." (PMID 38849574, 2024). "Notably, the augmented levels of CASP8 and GAMB were observed in the psoriasis-like dermatitis model, although their roles in the pathogenesis of psoriasis have not yet been investigated." (PMID 36110207, 2022). "Collectively, these results demonstrate that caspase-8-mediated apoptosis is responsible for the lethal dermatitis in mice lacking HOIP or HOIL-1 in keratinocytes and that RIPK3/MLKL-mediated necroptosis does not contribute to the disease." (PMID 30254289, 2018). "Since deficiency of caspase-8 or FADD alone in epidermal keratinocytes triggers a RIPK3-dependent skin inflammation, we could not directly investigate the role of FADD or caspase-8 in the TNF-induced death of Sharpin-deficient keratinocytes in vivo." (PMID 25443631, 2014). "However, because inhibition of FADD/caspase-8 signaling in keratinocytes triggers TNFR1- and ZBP1-mediated necroptosis and skin inflammation, it is not possible to use conditional ablation of FADD or caspase-8 alone to assess the role of FADD/Caspase-8-induced signaling in ZBP1caE-het mice." (PMID 38849574, 2024). "Furthermore, these results indicate that the suppression of cpdm dermatitis seen by crossing to mice lacking RIPK1 kinase activity may, surprisingly, be due to RIPK1’s kinase activity being upstream of caspase-8 in mediating TNF-induced apoptosis." (PMID 25443632, 2014).